DNAJC2 (DnaJ heat shock protein family (Hsp40) member C2)
Description:
Acts both as a chaperone in the cytosol and as a chromatin regulator in the nucleus. When cytosolic, acts as a molecular chaperone: component of the ribosome-associated complex (RAC), a complex involved in folding or maintaining nascent polypeptides in a folding-competent state. In the RAC complex, stimulates the ATPase activity of the ribosome-associated pool of Hsp70-type chaperones HSPA14 that bind to the nascent polypeptide chain. When nuclear, mediates the switching from polycomb-repressed genes to an active state: specifically recruited at histone H2A ubiquitinated at 'Lys-119' (H2AK119ub), and promotes the displacement of the polycomb PRC1 complex from chromatin, thereby facilitating transcription activation.
Synonyms: MPHOSPH11; MPP11; ZRF1; ZUO1; zuotin
Tractability: PROTAC: ubiquitination databases record sites on it; its protein half-life has been measured.
Gene: Protein-coding gene on chromosome 7 (103,312,289 to 103,344,830, reverse strand). Ensembl gene ENSG00000105821.
Subcellular location: Nucleus; Cytoplasm, cytosol
Subcellular location (Human Protein Atlas): Cytosol
Pathways (Reactome):
Cellular responses to stimuli: Regulation of HSF1-mediated heat shock response
Gene Ontology:
Molecular function: chromatin binding; histone binding; Hsp70 protein binding; protein binding; RNA binding; ubiquitin-modified histone reader activity; ATPase activator activity; ribosome binding
Biological process: positive regulation of DNA-templated transcription; 'de novo' cotranslational protein folding; protein folding; regulation of cellular response to heat; chromatin organization; regulation of translational fidelity
Cellular component: cytoplasm; cytosol; nucleolus; nucleus; protein folding chaperone complex; nucleoplasm
Genetic constraint (gnomAD): Loss-of-function variants: 24 observed, 72.37 expected, observed/expected ratio (o/e) 0.33, 90% interval 0.24 to 0.47. The upper end of that interval is the gene's LOEUF score, 0.47, which puts it in group 2 of 6, group 1 being the genes least tolerant of losing a copy. Missense variants: 454 observed, 599.58 expected, observed/expected ratio (o/e) 0.76, 90% interval 0.7 to 0.82. Synonymous variants: 180 observed, 199.84 expected, observed/expected ratio (o/e) 0.9, 90% interval 0.8 to 1.02.
Homologues: Orthologues: chimpanzee DNAJC2 (99% identical), macaque DNAJC2 (99% identical), rabbit DNAJC2 (99% identical), dog DNAJC2 (98% identical), pig DNAJC2 (95% identical), mouse Dnajc2 (93% identical), rat Dnajc2 (92% identical), guinea pig DNAJC2 (85% identical), tropical clawed frog dnajc2 (82% identical), zebrafish dnajc2 (75% identical), Drosophila melanogaster CG10565 (45% identical), Caenorhabditis elegans dnj-11 (38% identical), and 6 more. Paralogues in human: DNAJC13 (19% identical), DNAJC1 (17% identical), DNAJC21 (15% identical), DNAJC16 (13% identical), DNAJC10 (12% identical), DNAJC11 (11% identical), DNAJC14 (11% identical), DNAJC17 (10% identical), DNAJC7 (10% identical), DNAJC18 (9% identical), DNAJC25 (9% identical), DNAJC3 (8% identical), and 8 more.
Diseases named in the same sentence as DNAJC2 in open-access papers:
DNAJC2 is named in the same sentence as 35 diseases in open-access papers, as found by Europe PMC text mining. Sharing a sentence is not in itself a finding about the gene and the disease. The quoted sentences say what the papers report.
breast carcinoma (5 papers, 2016 to 2021). "Results from a transcriptomic array indicated a series of newly described transcription factors including HOXB7, MEIS2, TCERG1, and DNAJC2, that were associated to poor outcome in HER2+ breast cancer subtype and downregulated by the MZ1-trastuzumab combination." (PMID 33741018, 2021).
gastric cancer (3 papers, 2021 to 2025). A primary or metastatic malignant neoplasm involving the stomach. "DNAJC2/ZRF1 protein levels are also upregulated in gastric cancer tissues as compared to non-tumor tissues, which is correlated with poor overall outcomes." (PMID 34948322, 2021).
leukemia (3 papers, 2013 to 2025). A malignant (clonal) hematologic disorder, involving hematopoietic stem cells and characterized by the presence of primitive or atypical myeloid or lymphoid cells in the bone marrow and the blood. "DNAJC2 protein has been identified as a leukemia-associated antigen." (PMID 30419062, 2018).
colorectal cancer (2 papers, 2021 to 2025). A primary or metastatic malignant neoplasm that affects the colon or rectum. "DNAJC2, a member of the M-phase phosphoprotein family frequently altered in head and neck squamous cell carcinomas, acts as an oncogenic driver in colorectal cancer." (PMID 41208974, 2025). "Moreover, miR-627-3p could reversely regulate DnaJ Heat Shock Protein Family (Hsp40) Member C2 (DNAJC2) and foster a tumor-inhibiting role in colorectal cancer." (PMID 34872454, 2021).
lung adenocarcinoma (2 papers, 2018 to 2021). A carcinoma that arises from the lung and is characterized by the presence of malignant glandular epithelial cells. "Mutations in three genes (DNAJC2, GMPPA, or MMRN2) are negatively associated with survival in lung adenocarcinoma." (PMID 33791386, 2021). "Mutations in GMPPA, DNAJC2, and MMRN2 were significantly associated with patient mortality in lung adenocarcinoma of Pan-Lung Cancer cohort." (PMID 30419062, 2018).
atherosclerosis (1 paper, 2020). A disease characterized by the build-up of fatty material and calcium deposition in the arterial wall resulting in partial or complete occlusion of the arterial lumen. "Consequently, TIA, AIS, cCI, and AMI caused by atherosclerosis were associated with the DNAJC2 Ab levels." (PMID 32904265, 2020). "The major finding of the current study was the elevated levels of DNAJC2-Ab in patients with atherosclerotic diseases, including stroke, AMI, DM, and CKD, which suggests that DNAJC2-Ab is potentially useful to evaluate the progress of atherosclerosis." (PMID 32904265, 2020). "Furthermore, the elevation in DNAJC2-Ab levels was an independent predictor of stroke and TIA, suggesting that DNAJC2-Ab could discriminate atherosclerosis leading to stroke." (PMID 32904265, 2020).
diabetic kidney disease (1 paper, 2020). Progressive kidney disorder caused by vascular damage to the glomerular capillaries, in patients with diabetes mellitus. "The most prominent association with DNAJC2 Abs was observed with type 1 CKD (diabetic kidney disease) and type 2 CKD (nephrosclerosis)." (PMID 32904265, 2020).
lung carcinoma (1 paper, 2018). "In LUAD of Pan-Lung Cancer cohort, mutations in DNAJC2, GMPPA, MMRN2, DRD3, and SETX were significantly associated with survival status, and those in DNAJC2, MMRN2, and SETX were significantly associated with overall survival." (PMID 30419062, 2018). "In LUAD of Pan-Lung Cancer cohort, mutations in GMPPA, DNAJC2, and MMRN2 showed significant negative associations with survival of patients while mutations in DRD3 and SETX showed significant positive association with survival." (PMID 30419062, 2018).
posterior fossa ependymoma (1 paper, 2022). A high grade ependymoma that is located within the posterior fossa. "Interestingly, 6/7 of the constrained genes in which pLoF variants were found in patients with posterior fossa ependymoma show particularly high expression levels in cerebellar tissue (UHRF2, FOXO3, CDC42BPA, ZMYM2, CHD6 and DNAJC2)." (PMID 36008825, 2022).
Stroke (1 paper, 2020). Sudden impairment of blood flow to a part of the brain due to occlusion or rupture of an artery to the brain. "Using the DNAJC2-Ab cutoff value of 9837, univariate logistic regression analysis revealed that elevation in DNAJC2-Ab levels was associated with an increased risk of stroke [odds ratio (OR) 3.41, 95% confidence interval (CI): 2.44–4.76, p < 0.0001]." (PMID 32904265, 2020).
tumor (14 papers, 2016 to 2025). "Specifically, PIWIL4, SATB1, GSE1, NCOR1, SAP30L, ATM, and BMI1 were significantly downregulated in tumor tissues relative to normal controls, while BUB1, CHEK1, MASTL, DNAJC2, UBE2D1, and SSRP1 showed pronounced upregulation." (PMID 41208974, 2025). "The Basal subtype showed the highest number of specific upregulated genes (DNAJC2, DNAJC6, HSPA5, HSPA14 and CRYAA), DNAJA3 and CCT2 were upregulated in Luminal B, and DNAJB3 was only upregulated in HER2 tumours." (PMID 29954368, 2018). "DNAJC2/ZRF1 is shown to enhance H-Ras-induced cellular senescence of MEFs by interacting with the INK4/ARF locus and upregulating p16INK4a mRNA expression, thus displaying the tumor suppressive function." (PMID 34948322, 2021).
cancer (11 papers, 2013 to 2025). A tumor composed of atypical neoplastic, often pleomorphic cells that invade other tissues. "Finally, DNAJC2 has been described as a chromatin associated transcription factor linked to different types of cancer." (PMID 33741018, 2021). "For example, TBPT significantly suppressed a series of genes involved in DNA double-strand break repair, including LIG4, CENPF, DNAJC2, RECQL, SMC6 and BRCA2 (≥ 2-fold), which are also considered vital targets for treating cancer cells without affecting normal cells." (PMID 26986511, 2016).
infection (1 paper, 2014). The state of being infected such as from the introduction of a foreign agent such as serum, vaccine, antigenic substance or organism. "Only Dnajc2 was found to be down-regulated 14 days after infection in the liver tissues." (PMID 25542027, 2014).
DNAJC2 also shares sentences with these, for which no sentence is quoted: neuroblastoma (5 papers); acute myeloid leukemia (3); glioma (2); head and neck squamous cell carcinoma (2); brain tumor (1); breast invasive ductal carcinoma (1); breast tumors (1); colon cancer (1); Ewing sarcoma (1); glioblastoma (1); invasive breast carcinoma (1); lung squamous cell carcinoma (1); medullary breast carcinoma (1); melanoma (1); myeloid neoplasm (1); myeloma (1); nephrosclerosis (1); prostate carcinoma (1); renal carcinoma (1); small cell lung carcinoma (1); triple-negative breast carcinoma (1); viral infection (1).